TLR6 (toll like receptor 6)
Diseases named in the same sentence as TLR6 in open-access papers (continued):
Sharing a sentence is not in itself a finding about the gene and the disease.
cervical cancer (1 paper, 2024). A primary or metastatic malignant neoplasm involving the cervix. "When evaluating the gene expression patterns of TLR transcripts, specifically TLR1, TLR3, TLR4, TLR6, TLR7, TLR8 and TLR10, in HPV+ and HPV- cervical cancer tissue samples, we observed an increase in TLR4 expression and a decrease in TLR1 and TLR3 expression." (PMID 39208235, 2024). "Thus, although TLR4 is considered an important marker of HPV+ cervical cancer, alterations in the levels of TLR1, TLR3 and TLR6 observed in HPV+ samples may be the target of investigations related to the tumor inflammatory process." (PMID 39208235, 2024).
Chagas disease (1 paper, 2018). A parasitic infection caused by Trypanosoma cruzi. "Patients with different clinical manifestations of Chagas disease showed similar expression of TLR1, TLR3, TLR4, TLR5, TLR6, TLR7 and TLR9 mRNA." (PMID 30044791, 2018). "On the other hand, patients with different clinical manifestations of Chagas disease showed similar mRNA expression levels of TLR1, TLR3, TLR4, TLR5, TLR6, TLR7 and TLR9." (PMID 30044791, 2018).
colorectal cancer (1 paper, 2023). A primary or metastatic malignant neoplasm that affects the colon or rectum. "It was also reported that Lactobacillus-induced TLR6 signaling reduced tumor burdens and suppressed inflammation in inflammation-induced colorectal cancer." (PMID 37232814, 2023).
colorectal tumor (1 paper, 2021). "Furthermore, a decrease of TLR6 expression in colorectal tumor samples has been found compared to normal colon tissues." (PMID 34540825, 2021).
Cryptococcal meningitis (1 paper, 2023). Meningeal inflammation produced by cryptococcus neoformans, an encapsulated yeast that tends to infect individuals with acquired immunodeficiency syndrome and other immunocompromised states. "TLR1 rs5743563 T/T, TLR2 rs3804099 T/T, TLR6 rs3796508 G/A, and TLR6 rs3804099 C/T were associated with a higher risk of cryptococcal meningitis in HIV-negative patients, whereas rs5743563 and rs3804099 were associated with CSF cytokine expression." (PMID 36678440, 2023).
dental caries (1 paper, 2024). The decay of a tooth, in which it becomes softened, discolored, and/or porous. "In future gene association studies of dental caries, other genes involved in Toll-like receptor-mediated pathogen recognition and/or regulation, such as TLR1 (Toll-like receptor 1 gene), TLR6 (Toll-like receptor 6 gene), and MD-2 (myeloid differentiation-2 gene), should also be considered." (PMID 39000094, 2024).
depression (1 paper, 2025). "Regarding TLR6, only one study found that although TLR6 mRNA levels in peripheral blood mononuclear cells (PBMCs) were unchanged in patients with depression, they dropped below levels seen in healthy controls following antidepressant treatment." (PMID 40558558, 2025).
diffuse cutaneous Leishmaniasis (1 paper, 2025). A form of LEISHMANIASIS, CUTANEOUS caused by Leishmania aethiopica in Ethiopia and Kenya, L. pifanoi in Venezuela, L. braziliensis in South America, and L. mexicana in Central America. "It has been reported that patients with diffuse cutaneous leishmaniasis exhibited a reduced number of NK cells, lower levels of cytokines, such as IFN-γ, and diminished TLR expression, as is the case of TLR1, TLR2, and TLR6." (PMID 39963187, 2025).
Dysmenorrhea (1 paper, 2017). Pain during menstruation that interferes with daily activities. "After statistical analysis confirmed that: The gene expression of TLRS (TLRS = TLR1 + TLR2 + TLR3 + TLR4 + TLR5 + TLR6 + TLR7 + TLR8 + TLR9) in severe and moderate dysmenorrhea group was significantly higher than that in minimal dysmenorrhea group in EU and EC (P < 0.05 or P < 0.01)." (PMID 28779087, 2017).
dysplasia (1 paper, 2016). A usually neoplastic transformation of the cell, associated with altered architectural tissue patterns. "TLR6 intensity increased from normal epithelium and gastric metaplasia towards intestinal metaplasia and high-grade dysplasia, which had clearly the highest TLR intensity." (PMID 27008696, 2016).
E. coli infection (1 paper, 2023). "The phagocytosis-promoting receptors were upregulated after E. coli infection, including complement receptor (CR1, CR3, and iC3b), integrins (αMβ2, αVβ3, and αVβ5), toll-like receptor (TLR2, TLR4, and TLR6), might accelerate the phagosome maturation." (PMID 36411420, 2023).
endocarditis (1 paper, 2018). Inflammation of the endocardium. "In endocarditis among TLRs, rs3775073 polymorphism within the TLR-6 gene is the only one actually reported to be associated with the decrease of endocarditis onset among Caucasian peoples." (PMID 30205488, 2018).
gastric cancer (1 paper, 2025). A primary or metastatic malignant neoplasm involving the stomach. "However, in another study, the expression of TLR1, TLR2, TLR4, TLR5 and TLR6 was associated with survival in gastric cancer, and only high cytoplasmic TLR2 expression was shown to be significantly associated with a poorer 5-year survival." (PMID 40362298, 2025).
glomerulonephritis (1 paper, 2016). A renal disorder characterized by damage in the glomeruli. "The authors demonstrated an increase of TLRs 1–9 mRNAs paralleling the progression of glomerulonephritis: at 5 weeks, only mRNAs for TLRs 1–4 and TLR6 were expressed in the absence of any infiltrating cells; at week 20, there was a wider and stronger expression of TLRs 1–9." (PMID 27635115, 2016).
gout (1 paper, 2022). A condition characterized by painful swelling of the joints, which is caused by deposition of urate crystals. "We identified 256 eccDNA-associated genes solely represented in gout patients compared to healthy controls, from which we identified a couple of genes involved in inflammatory response, including TLR6, IL2RA, PTGS1, MAPK13, CHRNA4, GCH1, and IL5." (PMID 35464862, 2022). "In particular, TLR6 is involved in the key signaling pathway of gout inflammatory response, the NF-kappaB signaling pathway." (PMID 35464862, 2022).
heart failure (1 paper, 2020). Inability of the heart to pump blood at an adequate rate to meet tissue metabolic requirements. "This demonstrated that TLR6 knockouts resulted in an improved heart failure phenotype that ventricular dilation and impaired contractility were partly restored." (PMID 32558367, 2020).
hyperuricemia (1 paper, 2020). An abnormally high level of uric acid. "In the end, we took advantage of tlr6 knockdown rats suffering from hyperuricemia and observed that tlr6 knockdown improved myocardial damage and left ventricular remodelling induced by sUA." (PMID 32558367, 2020). "In addition, the tlr6 knockdown rats suffering from hyperuricemia showed the lower level of IL‐1β and an ameliorative cardiac function." (PMID 32558367, 2020). "We next examined whether reducing TLR6 level with adenovirus was able to restore myocardial damage and to inhibit NLRP3 inflammasome activation in rats bearing hyperuricemia." (PMID 32558367, 2020).
hypothyroidism (1 paper, 2022). Abnormally low levels of thyroid hormone. "As an example, the most significant pathway detected by PANTHER is a toll-like receptor signaling pathway for co-cluster 111 comprised of hypothyroidism/myxedema and levothyroxine sodium medication, and genes TLR1, TLR6, and TLR10 in the cells—EBV-transformed lymphocytes tissue." (PMID 35987940, 2022).
Kawasaki disease (1 paper, 2017). A rare inflammatory disease characterized by an acute febrile, systemic, self-limiting, medium-vessel vasculitis primarily affecting children. "for helpful discussion of the TLR6 exonic variants and the International Kawasaki Disease Genetics consortium for the original GWAS dataset." (PMID 28151979, 2017).
keloid (1 paper, 2024). An irregularly shaped, elevated mark on the skin caused by deposits of excessive amounts of collagen during wound healing. "Among the genes induced in keloids are Tlr1, Tlr2, Tlr6, and Acod1, commonly up-regulated by bacteria." (PMID 39081787, 2024).
leishmaniasis (1 paper, 2021). Infectious disease that is transmitted through the bite of hematophagous female phlebotomine sand flies. "In diffuse cutaneous (DCL) leishmaniasis that is characterized by uncontrolled parasite dissemination and poor production of IFN-γ patients showed reduced NK cell numbers that down-regulated TLR2, TLR1 and TLR6 expression as well as reduced cytokine production, as compared to CL patients." (PMID 34691019, 2021).
leptospirosis (1 paper, 2021). A contagious bacterial infection caused by spirochetes of the genus Leptospira. "Polymorphisms in TLR6 and TLR10 were more frequent in animals negative for leptospirosis, neosporosis, viral diarrhea, and leukosis, suggesting that this chromosome has candidate genes for resistance to infections." (PMID 34070451, 2021).
leukemia (1 paper, 2022). A malignant (clonal) hematologic disorder, involving hematopoietic stem cells and characterized by the presence of primitive or atypical myeloid or lymphoid cells in the bone marrow and the blood. "Further studies are necessary to elucidate the role of the TLR1, TLR4, TLR5, TLR6, TLR9, and CD14 polymorphisms in the pathogenesis of leukemia." (PMID 36071076, 2022).
loiasis (1 paper, 2022). Loiasis is a form of filariasis (see this term), caused by the parasitic worm Loa loa, endemic to the forest and savannah regions of Central and Western Africa. "TLR2 and TLR6 are of particular importance, as filariae including the causative agents of LF, onchocerciasis and mansonellosis, but not loiasis, contain endosymbiotic Wolbachia bacteria, which trigger an inflammatory response through TLR2 and TLR6 recognition." (PMID 36389745, 2022).
lung adenocarcinoma (1 paper, 2022). A carcinoma that arises from the lung and is characterized by the presence of malignant glandular epithelial cells. "A recent study reported that TLR6, as a member of a novel gene signature, can predicts the prognosis of lung adenocarcinoma." (PMID 35860577, 2022).
lymph node metastases (1 paper, 2024). "Of the 95 lymph node metastases, analyzable samples were available for 70 (TLR1), 72 (TLR2), 77 (TLR4), 58 (TLR5), 76 (TLR6), 72 (TLR7), 76 (TLR8) and 70 (TLR9) cases." (PMID 38709790, 2024).
Mycobacterium infection (1 paper, 2023). Infections with bacteria of the genus Mycobacterium. "Interestingly, several research highlighted the role of TLR‐6 in mitigating Mycobacterium infection to which P. nobilis is regularly exposed to." (PMID 37546570, 2023).
mycoplasma infections (1 paper, 2010). "As lipoproteins from other mycoplasmas can stimulate cells using TLR2, our studies support a role of TLR2, along with TLR1 and/or TLR6, recognition in infection and disease pathogenesis in other mycoplasma infections, including those that affect humans." (PMID 20505832, 2010).
myocardial infarction (1 paper, 2018). Gross necrosis of the myocardium, as a result of interruption of the blood supply to the area, as in coronary thrombosis. "After myocardial infarction, gene expression levels of the plasma membrane localized Tlr2 and Tlr6 were significantly increased when compared to their healthy controls." (PMID 29538462, 2018). "In this study, we observed highly increased gene expression levels of Tlr1, Tlr2, Tlr6, Tlr7, Tlr8, Tlr9 as well as Irf7 in the scar tissue after myocardial infarction, indicating their relevance to a proper cardiac wound healing." (PMID 29538462, 2018).
myocarditis (1 paper, 2018). Myocarditis is a condition that is characterized by inflammation of the heart muscle (myocardium). "During acute CVB3-induced myocarditis most of the plasma membrane and intracellular localized TLRs showed an enhanced gene expression, however, Tlr2, Tlr3, Tlr6, Tlr7, and Tlr9 displayed by far the highest increase of mRNA expression during acute disease." (PMID 29538462, 2018). "In acute CVB3 myocarditis (7 days post infection (pi)) all plasma membrane localized TLRs showed an increased gene expression, however, the highest increase in gene expression levels displayed Tlr2 and Tlr6." (PMID 29538462, 2018). "At the chronic stages of myocarditis (28 days pi CVB3) only Tlr2, Tlr4 and Tlr6 showed still an increased gene expression." (PMID 29538462, 2018).
neurocysticercosis (1 paper, 2022). "Of them, the heterodimer of TLR2/TLR6 might participate in recognition of the T. regenti infection similarly to murine neurocysticercosis." (PMID 35120185, 2022).
neurosyphilis (1 paper, 2023). Infection of the brain or spinal cord by Treponema pallidum. "Laboratory-defined neurosyphilis is associated with a common TLR1 polymorphism, while clinically and laboratory-defined neurosyphilis are both associated with common TLR2 and TLR6 polymorphisms." (PMID 37937275, 2023).
non-alcoholic steatohepatitis (1 paper, 2016). "TLR6 expression in PBMCs from non-alcoholic steatohepatitis (NASH) patients was significantly higher when compared to those from simple steatosis." (PMID 27834919, 2016).
otitis (1 paper, 2021). "This study showed that the expression of TLR6 mRNA was significantly lower in the otitis-prone group than in the non-otitis–prone group, with similar results to those observed for TLR2 mRNA." (PMID 34360632, 2021). "Another study compared the expression of TLR6 in middle ear effusion after classifying pediatric OME patients who had undergone ventilation tube insertion into otitis-prone and non-otitis–prone groups." (PMID 34360632, 2021).
ovarian tumor (1 paper, 2013). "Versican V1 produced by ovarian tumor cell leads to activation of TLR2 and its coreceptors TLR6 and CD14 in macrophages." (PMID 23424670, 2013).
pancreatitis (1 paper, 2015). Inflammation of the pancreas. "Other Toll-like receptors were also associated with pancreatitis, including TLR3 and TLR6, whose genetic polymorphisms are associated with the occurrence of severe pancreatitis." (PMID 26347203, 2015).
paraplegia (1 paper, 2015). Complete paralysis of the lower half of the body including both legs, often caused by damage to the spinal cord. "This vulnerability decreased with age as TLR6-/- mice suffering from paraplegia were found to be able to recover from it." (PMID 26226614, 2015).
periodontitis (1 paper, 2022). An acute or chronic inflammatory process that affects the tissues that surround and support the teeth. "In a study on HIV-positive North American patients with periodontitis, 8 SNPs in 6 TLR genes (TLR1 (n = 2), TLR2 (n = 1), TLR4 (n = 1), TLR6 (n = 1), TLR8 (n = 2), and TLR9 (n = 1)) were positively associated with P. gingivalis (2 SNPs), T. denticola (6 SNPs), and T. forsythia (1 SNP)." (PMID 35122548, 2022).
primary open-angle glaucoma (1 paper, 2025). "The aim was to analyze the association of the TLR2 (rs5743708), TLR3 (rs3775291), TLR4 (rs4986790, rs4986791) and TLR6 (rs5743810) polymorphisms with primary open-angle glaucoma in patients of Western Siberia." (PMID 40144379, 2025).
pulpitis (1 paper, 2017). Inflammation of the dental pulp. "Furthermore, deciduous pulps with pulpitis suffered higher expressions of proinflammatory cytokines (IL-6 and MCP-1) and innate immune response (TLR1, TLR2, TLR3, TLR6, and TLR8) than pulps without pulpitis." (PMID 28377925, 2017).
scrapie (1 paper, 2022). A fatal disease of the nervous system in sheep and goats, characterized by pruritus, debility, and locomotor incoordination. "In the thalamus, TLR6, MyD88, and CD36 were significantly upregulated in the scrapie-infected group (p < 0.05), while TLR2 and TLR3 displayed a tendency towards upregulation (p < 0.1)." (PMID 35408945, 2022).
Thrombocytopenia (1 paper, 2008). A reduction in the number of circulating thrombocytes. "A major group of genes (GMCSF, RANTES, IL2, INFγ, TLR6, CCR2A, IL-6, CKR-4) causing thrombocytopenia and vascular permeability was also found to be up-regulated in all three cell types." (PMID 19117515, 2008).
viral pneumonia (1 paper, 2023). Inflammation of the lung parenchyma that is caused by a viral infection. "Alterations in genes involved in the destruction of bacteria (LYST) and bacterial detection by the immune system (TLR6 and TLR4) could possibly increase susceptibility to bacterial infections secondary to viral pneumonia." (PMID 37985737, 2023).